PAX3 (paired box 3)
Diseases named in the same sentence as PAX3 in open-access papers (continued):
Sharing a sentence is not in itself a finding about the gene and the disease.
Waardenburg syndrome (continued). "In humans, as for some mutations in MITF, protein-changing variants in PAX3 have been shown to cause a similar form of Waardenburg syndrome, which is characterized by wide set eyes, hearing loss and regions of depigmentation in the iris, hair and skin." (PMID 31703548, 2019). "An autosomal dominant frameshift variant, NM_001127366.2(PAX3):c.870_871insC, was discovered and is known to be the genetic cause of Waardenburg Syndrome." (PMID 31138263, 2019). "Neural tube closure is regulated by Paired box 3 (PAX3), a transcription factor believed to cause many cases of the developmental condition called the Waardenburg syndrome." (PMID 29790000, 2018). "Similar to our mouse study, cases of hydrocephalus have been reported in some Waardenburg syndrome patients with various PAX3 heterozygous mutations." (PMID 26949601, 2016). "We identified a novel missense c.788T>G mutation in PAX3 in a family with Waardenburg syndrome with intrafamilial phenotypic heterogeneity." (PMID 23378733, 2013). "The reported PAX3 mutations in Chinese patients with Waardenburg syndrome." (PMID 41195004, 2025). "Taken together, these results suggest that Pax3 is required for the development of neural crest cell-derived cochlear melanocytes, whose absence may contribute to congenital hearing loss of Waardenburg syndrome in humans." (PMID 38278860, 2024). "These diversities in phenotype may also be reflected in the variable degrees of hearing loss in type 1 and 3 Waardenburg syndrome caused by various PAX3 gene mutations." (PMID 38278860, 2024). "Our results suggest that loss of Pax3 leads to reduction of cochlear melanocytes, which may contribute to congenital hearing loss in Waardenburg syndrome." (PMID 38278860, 2024). "There are also reports of homozygous PAX3 mutations among type 3 Waardenburg syndrome patients." (PMID 38278860, 2024). "Taken together, these results suggest that Pax3 is required for the development of neural crest cell-derived cochlear melanocytes, whose absence may contribute to congenital hearing loss of Waardenburg syndrome in human." (PMID 37333245, 2023). "Six genes involved in Waardenburg syndrome include PAX3 (encoding the paired box 3 transcription factor), MITF (microphthalmia-associated transcription factor), EDN3 (endothelin 3), EDNRB (endothelin receptor type B), SOX10 (encoding the Sry bOX10 transcription factor), and SNAI2 (snail homolog 2)." (PMID 35790984, 2022). "Disruption of pax3 caused the pigmentation defects at limbs revealed by lack of pigments and more transparent skin (7 out of 7), and severe defects of paralyzed upper limbs (3 in 7), which resembled some symptoms of Waardenburg syndrome in human." (PMID 27042291, 2016). "PAX3 haploinsufficiency is known to cause Waardenburg syndrome." (PMID 25928000, 2015). "In humans, PAX3 is one of six genes mutated in Waardenburg syndrome, which is characterized by a range of neural crest related phenotypes including minor facial dysmorphism manifest as a broad nasal root and an increased distance between the medial canthi or corners of the eye (telecanthus)." (PMID 23028347, 2012). "Thus, both heterozygous and homozygous PAX3 mutations are associated with Waardenburg syndrome." (PMID 38278860, 2024). "The deletion included the entire PAX3 gene, which was responsible for the Waardenburg syndrome phenotype, and 36 neighboring genes, including EPHA4." (PMID 40662934, 2025). "Neurocristopathies can be caused by pathogenic variants of master neural crest regulators, for example, SOX10 in Hirschsprung’s disease and Waardenburg syndrome or PAX3 in Waardenburg syndrome." (PMID 39418292, 2024). "As such, a mouse model (e.g. Pax3 hypomorph) that more accurately models human Waardenburg syndrome is needed." (PMID 38278860, 2024).
Waardenburg syndrome (continued). "Pax3 knockout mice, which model symptoms of Waardenburg syndrome, lack a transcription factor necessary for cardiac neural crest cell (cNCC) migration and proliferation in the pharyngeal arches and embryonic outflow tract." (PMID 38713657, 2024). "Previously, Pax3 heterozygous mice (splotch mice, Sp) show normal hearing even though they have patchy pigmentation of skin hair like human Waardenburg syndrome patients." (PMID 38278860, 2024). "One novel variant in the USH2A gene was detected in one individual, and one novel and one known variant were also detected in the PAX3 and MITF genes, respectively, in two persons with Waardenburg syndrome and profound HL." (PMID 31850270, 2019). "The rare combination of Waardenburg syndrome phenotype and short stature observed in our patient can be explained by the haploinsufficiency of both PAX3 and EPHA4 genes involved within the deletion." (PMID 25928000, 2015). "Pathogenic variants in PAX genes underlie diverse congenital disorders such as aniridia (PAX6), renal coloboma syndrome (PAX2), otofaciocervical syndrome with immunodeficiency (PAX1), Waardenburg syndrome (PAX3), maturity-onset diabetes of the young (PAX4), and tooth agenesis (PAX9)." (PMID 41751498, 2026). "Mutations in the PAX genes are associated with congenital human diseases related to eye development and deafness, including Aniridia and Peter’s anomaly (PAX6) and Waardenburg syndrome (PAX3), suggesting that the PAX genes play a central role in the development of the nervous system." (PMID 40002695, 2025). "Since PAX3 is linked with Waardenburg syndrome with variable clinical features, it was not included in the HearingCare_81 panel and thus not considered as the molecular etiology of this case." (PMID 31138263, 2019). "PAX3 has been associated with syndromic HSCR, i.e. Waardenburg syndrome." (PMID 30616633, 2019). "Notably, a proline to leucine substitution at the homologous site of PAX3 has been reported to be responsible for a case of Waardenburg syndrome (P50L, rs104893650." (PMID 29023497, 2017). "As scoliosis is not typically associated with Waardenburg syndrome caused solely by PAX3 pathogenic variants, we hypothesize that the deletion of EPHA4 may be responsible for the IS phenotype in this patient." (PMID 40662934, 2025). "Previously, Pax3 mutants including Sp, Sp2H and Pax3-Cre mice have been analyzed for cochlear development and those heterozygous mice are identified by the presence of patchy pigmentation of skin hair, which is one of the major phenotypes of type 1 and 3 Waardenburg syndrome patients." (PMID 38278860, 2024). "Moreover, PAX3 mutations have also been identified in another rare disorder called craniofacial-deafness-hand syndrome (CDHS), which is considered to be an allelic variant of Waardenburg syndrome." (PMID 36329483, 2022). "Mutations of different genes like MITF (microphthalmia-associated transcription factor), PAX3 (Paired Box Gene 3), SOX10, and EDNRB (endothelin receptor type B, gene) have been noted in causing mild or incomplete phenotypic expression of symptoms in Waardenburg syndrome." (PMID 31998473, 2020). "Thus, possible candidates for white coat colour (KIT on BTA6, KITLG on BTA5, PMEL on BTA5, TYR on BTA29) and other Waardenburg syndromes (WS) including PAX3 (WS1, WS3; on BTA2), EDNRB (WS4a; on BTA12), EDN3 (WS4b; on BTA13) and SOX10 (WS2e, WS4c; on BTA5) could be clearly excluded." (PMID 22174915, 2011). "Although the Waardenburg syndrome genes PAX3, SOX10, MITF, EDN3 and EDNRB were not dramatically affected at the mRNA level, expression of the piebaldism gene KIT was significantly down-regulated upon loss of YY1." (PMID 22570637, 2012). "Although the Pax3 knockout mice do not fully phenocopy Waardenburg syndrome in human, our and others’ results suggest that disruption of cochlear melanocytes as a result of Pax3 deficiency may contribute to their hearing loss." (PMID 38278860, 2024).
sarcoma (26 papers, 2010 to 2026). A usually aggressive malignant neoplasm of the soft tissue or bone. "Transfection of sarcoma-derived cell lines with expression vectors encoding PAX3-FKHR resulted in transactivation of a co-transfected IGF1R promoter construct, whereas PAX3 exhibited a reduced potency in comparison to the chimera." (PMID 29455671, 2018). "This can cause confusion, but biphenotypic sinonasal sarcoma features PAX3 gene rearrangement." (PMID 41246587, 2025). "Examples of antibodies serving as surrogate markers of sarcoma-specific genetic aberrations, e.g., fusions, amplifications, and point mutations, include SS18-SSX or SSX, TFE3, SMARCB1, BCOR, MDM2, DDIT3, and PAX3." (PMID 40526340, 2025). "Sarcomas are traditionally classified in two major genetic groups: the first group includes sarcomas with simple karyotypes and specific genetic alterations like EWS-ATF1 fusions in Ewing sarcomas, KIT mutations in GISTs, or PAX3-FKHR fusions in alveolar rhabdomyosarcomas." (PMID 32839432, 2020). "Also, increased expression of ASNS compared to normal human muscle was detected in 9 of 9 human sarcoma cell lines analyzed by PCR, including the PAX3:FOXO1-positive human RMS cell line Rh30." (PMID 26499495, 2015). "Similar to the Prx-Cre;Ews-Fli1 studies, these mice did not develop sarcomas, but did display numerous congenital defects, suggesting the Pax3-Fkhr fusion gene is important in normal murine development but requires additional genetic hits for sarcoma development." (PMID 23036318, 2012). "RMS cells express the lowest levels of EpCAM and E-cadherin among all sarcoma histotypes due to PAX3-FOXO1 transcription factor, which antagonizes wild-type Pax3-induced cell aggregation and epithelioid changes." (PMID 34063272, 2021). "As expected, lung tumors with driver fusions harbored mostly EML4/ALK fusions, sarcomas were driven mostly by EWSR1-related and PAX3/FOXO1 fusions, while hematologic malignancies with a spectrum of BCR/ABL1, KMT2A-related, and IGH/MYC fusions." (PMID 33889297, 2021). "PAX3/FOXO1 is the driver oncofusion in 70% of FP‐RMS and promotes phenotypes critical to both sarcoma growth and dissemination." (PMID 32697014, 2020). "It is thus clear that unravelling the transcriptional regulatory mechanisms of PAX3, FOXO1 and the oncogenic PAX3:FOXO1 gene should help to identify the elusive cell type of origin for these sarcomas." (PMID 28615069, 2017). "In sarcoma-derived cell lines, the PAX3-FOXO1 fusion protein induces a more significant rise in IGF-1 levels as compared with PAX3 alone." (PMID 23638435, 2013). "Diagnostically, this result could be very significant in that it leaves the possibility that some clinical cases of undifferentiated pleomorphic sarcomas may in fact express Pax3:Foxo1A, but in the context of pRb loss would not be tested for Pax3:FoxO1A given their histological appearance." (PMID 24274149, 2013). "Altogether, cross-species comparison of transcriptome, methylome, and histology data revealed a coherent picture, indicating conservation of human sarcoma biology across the sarcoma EPO-GEMM cohort, especially for bona fide fusion-driven sarcomas SS18::SSX, NTRK-Mono, PAX3::FOXO1 and ASPSCR1::TFE3." (PMID 40523919, 2025).
sarcoma (continued). "Furthermore, they provide a strong rationale for the use of PROTACs in targeting gene fusions in paediatric sarcoma such as EWSR1::FLI1 and PAX3::FOXO1." (PMID 40983796, 2025). "Pathologists might consider addressing this possibility in cases of pediatric and adolescent undifferentiated sarcomas and consider FISH for PAX3:FOXO1 in atypical cases." (PMID 25030697, 2014). "The manner in which Ets1 regulation by PAX3/FOXO1 and EWS/Fli1 tracks with the effects of the respective oncofusions on metastatic phenotypes suggests that Ets1 may have a more general, important role in sarcoma metastasis." (PMID 32697014, 2020). "Molecular classification has been proposed, dividing RMS into two basic groups: fusion-positive RMS (either PAX7::FOXO1 enriched or PAX3::FOXO1 enriched) and fusion negative RMS (which is further sub-divided into well differentiated RMS, moderately differentiated RMS, and undifferentiated sarcomas)." (PMID 39020398, 2024).
Ewing sarcoma (18 papers, 2005 to 2025). A small round cell tumor that lacks morphologic, immunohistochemical, and electron microscopic evidence of neuroectodermal differentiation. "A large diversity offusion oncogenes was observed, primarily in one tumor, the three most commonbeing: EWSR1::Fli1 (n = 13) observed in Ewing sarcomas, PAX3::FOXO1 (n = 12) inrhabdomyosarcomas, and ETV6::RUNX1 (n = 8) in childhood leukemias." (PMID 40093400, 2025). "We confirmed DNA-binding specificity of the purified protein by comparing its binding with oligonucleotides specific for PAX3::FOXO1 or EWS::FLI1 (a tumor-specific fusion oncoprotein found in Ewing sarcoma) using SPR." (PMID 37732905, 2023). "Like EWS/FLI of Ewing sarcoma, the PAX3/FOXO1 alters the function of other chromatin regulatory factors." (PMID 36686841, 2022). "Taken together, the relationship between LSD1 and PAX3/FOXO1 shows many parallels to LSD1 and EWS/FLI in Ewing sarcoma, supporting LSD1 as a promising therapeutic target in this disease." (PMID 36686841, 2022). "RMS is thought to originate from myogenic precursors expressing PAX3, thus—due to its expression in most RMS tumors —PAX3 has been tested in flow cytometry as a marker for circulating RMS cells, even if not for differential diagnosis since its expression has been described also in Ewing sarcoma." (PMID 34063272, 2021).
Waardenburg syndrome type 1 (18 papers, 2010 to 2025). Waardenburg syndrome type 1 (WS1) is a subtype of Waardenburg syndrome (WS), disorder characterized by congenital deafness, minor defects in structures arising from neural crest resulting in pigmentation anomalies of eyes, hair, and skin, in combination with dystopia canthorum. "Mutations in Pax3 are associated with Waardenburg syndrome type I, a rare neurocristopathy characterized, among others, by the widening of the nasal bridge area 55–57." (PMID 41253813, 2025). "Heterozygous mutations in human PAX3 gene cause type 1 Waardenburg syndrome, which is characterized by telecanthus (widely spaced eyes), heterochromia iridis, patchy pigmentation of hair and skin, and profound sensorineural hearing loss." (PMID 38278860, 2024). "In F9, the proband (III-3) had the phenotype of PAX3-related Waardenburg syndrome type 1 (WS) (congenital hearing loss, heterochromia iridis, telecanthus and hypopigmentation of hair and skin)." (PMID 34276053, 2021). "PAX3 is a gene known for being causative of Waardenburg syndrome type 1 and 2, a disease characterized by HL, pigmentation abnormalities and, in some cases, dystopia canthorum or other additional features." (PMID 33105617, 2020). "Screening of mutations in the paired box 3 (PAX3) gene in three generations of a Turkish family with Waardenburg syndrome type 1 (WS1)." (PMID 23378733, 2013). "The importance of Pax3 in dorsal neural tube and neural crest patterning and differentiation is evident in the human syndromes associated with Pax3 mutations (Waardenburg syndromes type I and type III) as well as in mouse Splotch mutants." (PMID 22390724, 2012). "Notably, both studies reported an association between PAX3 variants and anatomical changes in interorbital region, an intriguing finding given that mutations in PAX3 cause Waardenburg Syndrome type 1 which is characterized by hypertelorism among other morphological abnormalities." (PMID 27560520, 2016). "Rare mutations of PAX3 have been shown to cause Waardenburg syndrome type 1 (WS1)." (PMID 26926045, 2016).